RXFP1 (relaxin family peptide receptor 1)
Description:
Receptor for relaxins. The activity of this receptor is mediated by G proteins leading to stimulation of adenylate cyclase and an increase of cAMP. Binding of the ligand may also activate a tyrosine kinase pathway that inhibits the activity of a phosphodiesterase that degrades cAMP.
Synonyms: LGR7; RXFPR1
Tractability: Small molecule: it belongs to a druggable protein family. Antibody: UniProt places it where antibodies can reach, with high confidence; its Gene Ontology location is reachable by antibodies, with high confidence; UniProt predicts a signal peptide or a membrane-spanning region. PROTAC: a small molecule that binds it is known. Other modalities: a drug acting on it is in phase 2 or 3 trials.
Target class: Relaxin receptor; Relaxin-like peptide receptor (family A GPCR); Family A G protein-coupled receptor; Peptide receptor (family A GPCR); Membrane receptor
Chemical probes: ML290
Gene: Protein-coding gene on chromosome 4 (158,315,311 to 158,653,372, forward strand). Ensembl gene ENSG00000171509.
Subcellular location: Cell membrane
Pathways (Reactome):
Signal Transduction: G alpha (s) signalling events; Relaxin receptors
Gene Ontology:
Molecular function: G protein-coupled receptor activity; protein binding; G protein-coupled peptide receptor activity; hormone binding
Biological process: adenylate cyclase-activating G protein-coupled receptor signaling pathway; hormone-mediated signaling pathway; G protein-coupled receptor signaling pathway; signal transduction
Cellular component: plasma membrane; membrane
Genetic constraint (gnomAD): Loss-of-function variants: 34 observed, 46.86 expected, observed/expected ratio (o/e) 0.73, 90% interval 0.55 to 0.97. The upper end of that interval is the gene's LOEUF score, 0.97, which puts it in group 4 of 6, group 1 being the genes least tolerant of losing a copy. Missense variants: 520 observed, 613.41 expected, observed/expected ratio (o/e) 0.85, 90% interval 0.79 to 0.91. Synonymous variants: 180 observed, 213.64 expected, observed/expected ratio (o/e) 0.84, 90% interval 0.75 to 0.95.
Homologues: Orthologues: chimpanzee RXFP1 (99% identical), macaque RXFP1 (99% identical), pig RXFP1 (92% identical), rat Rxfp1 (86% identical), mouse Rxfp1 (85% identical), guinea pig RXFP1 (84% identical), dog RXFP1 (83% identical), rabbit RXFP1 (75% identical), tropical clawed frog rxfp1 (73% identical), zebrafish rxfp1 (62% identical). Paralogues in human: RXFP2 (52% identical), TLR3 (17% identical), TLR7 (17% identical), TLR8 (17% identical), TLR5 (16% identical), TLR10 (15% identical), TLR2 (15% identical), TLR1 (14% identical), TLR6 (14% identical), TLR4 (14% identical), VASN (14% identical), LRRC32 (13% identical), and 10 more.
Diseases named in the same sentence as RXFP1 in open-access papers:
RXFP1 is named in the same sentence as 64 diseases in open-access papers, as found by Europe PMC text mining. Sharing a sentence is not in itself a finding about the gene and the disease. The quoted sentences say what the papers report.
idiopathic pulmonary fibrosis (11 papers, 2017 to 2025). Idiopathic pulmonary fibrosis (IPF) is a nonneoplastic pulmonary disease that is characterized by the formation of scar tissue within the lungs in the absence of any known cause. "Studies showed that RXFP1 was associated with fibrotic diseases, such as lung fibrosis, kidney fibrosis and cardiac fibrosis." (PMID 36032660, 2022). "More importantly, RXFP1 expression was reported to be directly associated with pulmonary function in patients with idiopathic pulmonary fibrosis (IPF), and results showed that patients with IPF and high RXFP1 expression are more sensitive to relaxin-based therapies." (PMID 34039311, 2021). "The expression of RXFP1 is directly related to the pulmonary function of patients with Idiopathic Pulmonary Fibrosis." (PMID 38575860, 2024). "In a mouse experiment, RXFP1 expression alleviated symptoms of lung fibrosis and pulmonary arterial hypertension." (PMID 38575860, 2024). "Enhanced RXFP1 expression is associated with reduced levels of α-SMA, a marker protein for pulmonary fibrosis, suggesting a potential role in fibrosis inhibition." (PMID 38575860, 2024). "Expression of RXFP1 is decreased in idiopathic pulmonary fibrosis and mediates the effects of miR-144-3p in lung fibroblasts from patients with idiopathic pulmonary fibrosis." (PMID 31886214, 2019). "A previous study revealed that Rxfp1-deficient mice had increased lung collagen accumulation as early as 1 month of age, indicating that RXFP1 could delay the age-related progression of pulmonary fibrosis." (PMID 34039311, 2021). "Additionally, our research indicates that the evolution of the RXFP1 gene may be pivotal in controlling pulmonary fibrosis, thus facilitating the preservation of high pulmonary compliance and significantly improving respiratory efficiency while diving." (PMID 38575860, 2024). "Relaxin/insulin-like family peptide receptor 1 (RXFP1) mediates relaxin’s antifibrotic effects and has reduced expression in the lung and skin of patients with fibrotic interstitial lung disease (fILD) including idiopathic pulmonary fibrosis (IPF) and systemic sclerosis (SSc)." (PMID 34972106, 2021). "These genes were identified in reports of the alternative splicing in pulmonary fibrosis of known etiologies CD44, RXFP1, and CD146, a pulmonary fibrosis mouse model (FGFR2), and a genetic link between COVID-19 and IPF (DP99 and ATP11A)." (PMID 39937013, 2025). "Interestingly, unlike skin and lung fibrosis, dramatically increased hepatic expression of RXFP1 has been observed in a rat model of liver cirrhosis and—in contrast to lung and skin‐‐higher expression of RXFP1 is correlated with increased liver fibrosis in human." (PMID 32100955, 2020).
glioblastoma (8 papers, 2015 to 2023). The most malignant astrocytic tumor (WHO grade IV). "For example, CTRP8 promotes cell migration in human glioblastoma cells by activation of the RXFP1 involving the N-terminal “YAAFSVG” peptide motif present in the C1q globular domain of CTRP8." (PMID 37047812, 2023). "We identified CTRP8 as a ligand of the G protein‐coupled receptor relaxin family peptide receptor 1 (RXFP1) in glioblastoma multiforme (GBM)." (PMID 33960104, 2022). "Complement C1q tumor necrosis factor-related protein 8 (CTRP8) interacts with RXFP1 and induces the production and secretion of cathepsin B in glioblastoma cells, leading to laminin degradation and glioblastoma dissemination." (PMID 32727598, 2020). "RXFP1 (relaxin family peptide receptor 1) is known to have an important function in tumor growth and tissue invasion and is related to glioblastoma." (PMID 31487856, 2019). "The C1q/TNF‐related peptide 8 (CTRP8) has recently emerged as a novel ligand of the G protein‐coupled receptor RXFP1 in the fatal brain tumor glioblastoma (GBM)." (PMID 29949238, 2018). "Contrary to other tumors, malignant brain tumors such as Grade III anaplastic astrocytoma and Grade IV glioblastoma (GBM) express RXFP1 but fail to express RLN2." (PMID 29949238, 2018). "The C1Q‐TNF‐related peptide family member C1q tumor necrosis factor‐related peptide 8 (CTRP8) and its G protein‐coupled receptor relaxin family peptide receptor 1 (RXFP1) are emerging as a novel ligand–receptor system that can protect glioblastoma cells against DNA‐alkylating damage and apoptosis." (PMID 33960104, 2022). "We recently identified CTRP8 as a novel ligand for RXFP1 in human glioblastoma cells." (PMID 26322020, 2015). "Studies have revealed that RXFP1 is activated by both C1q-tumor necrosis factor-related protein 8 (CTRP8) and relaxin and contributes to growth and invasion of human glioblastoma." (PMID 31886214, 2019). "Binding of the leucine-rich G protein-coupled relaxin receptor RXFP1 to C1q-tumor necrosis factor-related protein 8 (CTRP8) ligand mediates increased GBM cell migration, protein kinase C pathway activation, and lysosomal protease cathepsin B production in glioblastoma progenitor cells." (PMID 37033981, 2023). "While this confirmed a key role for GBM‐expressed CTRP8 as oncogenic driver in human glioblastoma, it is conceivable that H2 relaxin has a similar effect on therapeutic resistance in RXFP1+ tumors outside of the brain." (PMID 29949238, 2018).
prostate carcinoma (7 papers, 2015 to 2025). A carcinoma that arises from epithelial cells of the prostate gland. "More recent studies suggested that Relaxin/RXFP1-mediated cancer growth and invasion in breast, thyroid and prostate cancers." (PMID 36032660, 2022). "Downregulation of RXFP1 in prostate cancer cells decreased tumor formation induced by these cells in nude mice." (PMID 32100955, 2020). "Overexpression of LDLa module of RXFP1 in prostate cancer cells resulted in a decrease in proliferation, soft agar colony formation, adhesion and invasion in vitro, and tumor growth in mouse model." (PMID 32100955, 2020). "Most of the cellular and molecular mechanisms involved in RXFP1-mediated cancer promotion have been established in breast, thyroid, and prostate cancer models." (PMID 26322020, 2015). "The siRNA-mediated knockdown of RXFP1 prevented the RLN2-induced increase in prostate cancer cell proliferation and invasiveness and induced apoptosis." (PMID 26322020, 2015). "Suppression of RXFP1 inhibits prostate cancer tumorigenesis, growth, and metastasis." (PMID 31886214, 2019). "This ΔH2 mutant was able to bind to RXFP1 and function as a partial antagonist to functional RLN2 in an in vivo xenograft model of prostate cancer." (PMID 26322020, 2015). "RXFP1-dependent and RLN2-induced proliferation of prostate carcinoma cells was mediated via a PI3K/Akt signaling pathway." (PMID 26322020, 2015). "In prostate cancer, RLN2/RXFP1 signaling increased cell migration and proliferation in androgen-receptor (AR)-dependent LNCaP and AR-independent PC3 prostate cancer cells and promoted growth in xenografts derived of androgen-independent PC3 prostate cancer cells." (PMID 26322020, 2015). "RXFP1 is expressed in both AR positive and negative prostate cancer and prostate cancer cell lines." (PMID 41347146, 2025). "Furthermore, in contrast with high RXFP1 expression on the prostate cancer cells in these studies, the lack of RXFP1 expression in both CRC and breast cancer cells resulted in unresponsiveness of tumor cells to RLN." (PMID 31278269, 2019).
liver fibrosis (6 papers, 2017 to 2026). "The mammalian hormone relaxin (RLN) is a potential inhibitor of liver fibrosis by stimulating a GPCR known as relaxin family peptide receptor 1 (RXFP1)." (PMID 34938271, 2021). "In both liver fibrosis models, the hepatic expression of RXFP1 increased by tenfold under constant liver injuries and decreased gradually during the resolution stage." (PMID 31278269, 2019). "The regulation of RXFP1 in liver fibrosis may be fundamentally different from that in lung, skin, and other fibrotic organs." (PMID 32100955, 2020). "Relaxin is a peptide which binds to the receptor RXFP1, thus reducing liver fibrosis." (PMID 31662751, 2019). "Herein, we strengthen the hypothesis that RXFP1 is a potential therapeutic target for treatment of human liver fibrosis, by showing upregulation of RXFP1 expression in human fibrotic liver tissues." (PMID 28883402, 2017). "In light of the potential clinical relevance of RXFP1 in liver fibrosis we first adopted a HTS approach as a quick and convenient route to potential identification of additional tool molecules for studying RXFP1 signalling in fibrosis-relevant models." (PMID 28883402, 2017). "In our efforts to generate a new medicine for liver fibrosis, we sought to identify improved small molecule functional mimetics of H2-RLX with selective, full agonist or positive allosteric modulator activity against RXFP1." (PMID 28883402, 2017). "However, the potential role of small molecule RXFP1 agonists/PAMs, including ML290, in treating liver fibrosis has not yet been investigated." (PMID 28883402, 2017).
breast carcinoma (4 papers, 2008 to 2019). "In an in vitro brain metastasis model, RLN2 promoted the invasion of RXFP1-expressing MCF-7 human breast cancer cells into brain tissue slices." (PMID 26322020, 2015). "Functionality of RXFP1 in MDA-MB-231 human breast cancer cells was determined by the increase in intracellular cAMP production following exposure to recombinant human RLN2 (rhRLN2)." (PMID 18718015, 2008). "In vivo, we could show that elevated relaxin-2 serum levels in breast cancer patients correlate with metastatic disease and high RXFP1 mRNA levels are an independent marker of metastasis and shortened survival in dogs." (PMID 23963762, 2014). "Oligonucleotide primers employed at melting temperatures (TM in °C) used to determine the expression of RLN2, human RXFP1 relaxin receptor (RXFP1), S100A4 and 18S transcripts in human breast cancer cell lines and xenograft tumours." (PMID 18718015, 2008). "Although in vivo studies in rat uterus have provided evidence for a crosstalk between RXFP1 and ERα and demonstrated ERα-mediated oestrogenic effects with relaxin treatment, a direct oestrogenic action of relaxin in breast cancer has not been described." (PMID 18718015, 2008).
endometritis (3 papers, 2024 to 2025). An acute or chronic, usually bacterial infectious process affecting the endometrium. "In the buffaloes affected by endometritis, the expression levels of the RXFP1, NDUFS5, TGF-β, SOD3, CAT, and GPX genes were significantly reduced." (PMID 39195794, 2024). "Buffaloes with endometritis showed significantly decreased levels of expression of the NDUFS5, RXFP1, TGF-β, CAT, SOD3, and GPX transcription factors." (PMID 40266925, 2025). "The RXFP1, NDUFS5, TGF-β, SOD3, CAT, and GPX genes were expressed at substantially lower levels in endometritis-affected buffaloes." (PMID 38459095, 2024).
heart failure (3 papers, 2020 to 2023). Inability of the heart to pump blood at an adequate rate to meet tissue metabolic requirements. "Since, deterioration of kidney function is an important prognostic factor for worsening heart failure, RXFP1 activation by restoring renal blood flow and kidney function is anticipated to be beneficial for the treatment of acute decompensated heart failure." (PMID 36443381, 2022). "In human heart tissue from healthy controls, RXFP1 is also the most abundant among all four receptors, and is significantly decreased in tissue of patients with end stage heart failure (obtained at the time of heart transplantation)." (PMID 32226528, 2020). "Therefore, relaxin’s receptor, relaxin family peptide receptor 1 (RXFP1), is a potential target for the treatment of fibrosis and related disorders, including heart failure." (PMID 37047588, 2023).
lung adenocarcinoma (3 papers, 2021 to 2022). A carcinoma that arises from the lung and is characterized by the presence of malignant glandular epithelial cells. "It was worth noting that the expression of RXFP1, AVPR2, ADRB1 and VIPR1 had significantly effect on the survival of patients with lung adenocarcinoma." (PMID 36032660, 2022). "Our bioinformatic analysis identified six downregulated DEGs (EDNRB, RXFP1, P2RY1, CALCRL, TEK, and ANGPT1) between lung adenocarcinoma and normal lung tissues based on two different microarray datasets." (PMID 34039311, 2021).
ovarian carcinoma (3 papers, 2020 to 2022). A malignant neoplasm originating from the surface ovarian epithelium. "Cells overexpressing recombinant human RXFP1, endothelial EA.hy926 (EA.hy926_RXFP1) or HEK (HEK_RXFP1) cells or with endogenous RXFP1 expression [OVCAR5 (Ovarian Carcinoma cells)] were used." (PMID 36443381, 2022). "RXFP1 was a receptor for relaxins, which was a short circulating peptide hormone and was found to be upregulated in patients with epithelial ovarian cancer." (PMID 32647070, 2020). "Furthermore, relaxin/RXFP1 inhibition reduced ovarian cancer cell viability and reversed cisplatin resistance." (PMID 35625966, 2022).
scleroderma (3 papers, 2017 to 2023). Scleroderma is a rare autoimmune connective tissue disorder characterized by abnormal hardening of the skin and, sometimes, other organs. "Therefore, restoring RXFP1 expression in fibroblasts from scleroderma patients contributes to the anti-dermal fibrotic effect of RLX." (PMID 37123405, 2023). "A study indicates that enriched genes including MPO (myeloperoxidase), RXFP1, CXCL11, CTNND2, BMPR2, TLR3, CCR2, and CAV1 are altered expressed in scleroderma." (PMID 38137330, 2023).
systemic sclerosis (3 papers, 2020 to 2023). A chronic disorder, possibly autoimmune, marked by excessive production of collagen which results in hardening and thickening of body tissues. "The failure of antifibrotic effects in systemic sclerosis patients by relaxin may be the result of reduced expression of its receptor relaxin family peptide receptor 1 (RXFP1) in the fibrotic tissues." (PMID 32100955, 2020).
Anxiety (2 papers, 2023 to 2025). Intense feelings of nervousness, tension, or panic often arise in response to interpersonal stresses. "We also identified differentially expressed genes involved in anxiety, mood, emotion (Cartpt, Snap25, Rxfp1, Nr1d1, Sept5), and neuropsychiatric disorders (YWHA-family)." (PMID 40978196, 2025).
asthma (2 papers, 2022 to 2023). "For example, RXFP1 can be knocked out in animal models by gene editing technology to observe its effect on the pathological process of asthma." (PMID 38013370, 2023). "In lung diseases characterized by fibrosis, RXFP1 gene and protein expression was found to be reduced, and in biopsy samples taken from asthma patients RXFP1 was found to be lower." (PMID 35955554, 2022). "In summary, RXFP1 may play a key role in the pathogenesis of asthma, but the specific mechanism needs to be clarified by further studies." (PMID 38013370, 2023). "In addition, the effect of RXFP1 gene expression on asthma symptoms can also be observed through pharmacological intervention." (PMID 38013370, 2023). "Understanding the role of RXFP1 in asthma may help to develop new therapeutic strategies and improve the quality of life of patients with asthma." (PMID 38013370, 2023). "However, regarding the specific role of RXFP1 in asthma, existing studies are not deep enough, and further experiments are needed to explore." (PMID 38013370, 2023).
brain cancer (2 papers, 2015 to 2016). A primary or metastatic malignant neoplasm affecting the brain. "Recently, we have identified the secreted protein, CTRP8, a member of the C1q/tumor necrosis factor-related protein (CTRP) family, as a novel ligand of the relaxin receptor, RXFP1, with functions in brain cancer." (PMID 26322020, 2015).
endometrial cancer (2 papers, 2018 to 2019). Primary or metastatic malignant neoplasm involving the endometrium (mucous membrane that lines the endometrial cavity). "This is the first study addressing RLN2-induced cellular invasion through RXFP1 signal transduction, β-catenin phosphorylation, and loss of E-cadherin in in vitro endometrial cancer cells." (PMID 30126180, 2018). "Relaxin 2/RXFP1 Signalling induces cell invasion via the beta-catenin pathway in endometrial cancer." (PMID 31886214, 2019). "It was also reported that RXFP1 mRNA is expressed in endometrial cancer tissues, however its influence on cancer cell behavior remained unclear." (PMID 30126180, 2018). "In this study, we first demonstrated the expression of RXFP1 in endometrial cancer tissues." (PMID 30126180, 2018). "In endometrial cancer, RLN increases MMP-2 or MMP-9 expression by binding to RXFP1." (PMID 30126180, 2018).